GFAP (glial fibrillary acidic protein)
Diseases named in the same sentence as GFAP in open-access papers (continued):
Sharing a sentence is not in itself a finding about the gene and the disease.
ischemic stroke (continued). "GFAP is a prominent astrocyte intermediate filament protein that rises quickly in hemorrhagic stroke but has a blunted or delayed response with ischemic stroke." (PMID 40949500, 2025). "SERS spectra were analyzed using ML to distinguish between hemorrhagic and ischemic stroke, mimicked by different concentrations of GFAP." (PMID 40136933, 2025). "In contrast, an ischemic stroke induced significant morphological changes, including increased GFAP immunoreactivity, extensive branching, and hypertrophy." (PMID 41373489, 2025). "Prediction of functional outcome after severe ischemic stroke was more accurate using the blood-based biomarkers NfL and GFAP." (PMID 38400734, 2024). "In conclusion, this is the first study demonstrating the potential incremental prognostic value of serum NfL and GFAP predicting good functional outcome 3 months after severe ischemic stroke." (PMID 38400734, 2024). "Patients with ischemic stroke (n = 21) showed median plasma GFAP concentrations of 110 pg/mL (IQR 29–651.5)." (PMID 38581002, 2024). "Other reports show an increased ipsilateral GFAP density after endothelin-1-induced ischemic stroke." (PMID 38674304, 2024). "In contrast, in ischemic stroke, GFAP is released with delay, as necrosis in ischemic stroke usually does not occur within the first hours after symptom onset." (PMID 38581002, 2024). "Together with these previous proposals, we tentatively believe that GFAP was observed as a best biomarker for predicting poor outcome in ischemic stroke patients." (PMID 38216970, 2024). "Reactive astrogliosis occurs after ischemic stroke through morphological changes and increased GFAP expression." (PMID 37353794, 2023). "Results showed that GFAP concentrations were higher in ICH than in ischemic stroke (1.91 μg/L (0.41–17.66) vs. 0.08 μg/L (0.02–0.14)." (PMID 37511304, 2023). "In previous studies on minor-to-moderate ischemic stroke, NfL and GFAP showed a fair value as prognostic factors to predict short- and middle-term functional outcomes as well as all-cause mortality." (PMID 38017278, 2023). "Decreased astrocyte activation in GFAP-/-Vim-/- mice with an ischemic stroke resulted in larger infarct size." (PMID 39816762, 2023). "We measured β-syn, GFAP and NfL in serum samples collected one day after admission in 30 adult patients with moderate-to-severe ischemic stroke due to middle cerebral artery (MCA) occlusion." (PMID 38017278, 2023). "In order to determine the cell type that produced LDs after ischemic stroke, we co-stained astrocyte-specific marker GFAP, neuron-specific marker NeuN and microglia/macrophage marker IBA1 with BODIPY." (PMID 37450211, 2023). "First, we examined the expression of the astrocyte activation marker, GFAP, on Day 28 after ischemic stroke." (PMID 36841833, 2023). "The ischemic stroke was induced by photothrombosis in the cerebral cortex of SCID mice in which the ischemic cavity was surrounded by GFAP+ and S100β+ glial scar at day 14 and the cortex collapsed at day 30 without treatment." (PMID 37867250, 2023). "GFAP is a biomarker for differentiating between patients with ischemic stroke (IS) and hemorrhagic stroke (HS)." (PMID 38032374, 2023). "We envision that C3d+/GFAP+ A1 astrocytes represent a novel therapeutic target for ischemic stroke therapy." (PMID 35656116, 2022). "Several studies performed in different clinical settings showed a delayed GFAP release in patients with ischemic stroke, compared to hemorrhagic stroke, with a maximum concentration reached 2–4 days after ischemic stroke onset." (PMID 35813155, 2022). "An ischemic stroke, for example, is characterized by abnormal astrocyte activity, such as hyperplasia and hypertrophy, which increases GFAP immunoreactivity during the recovery process." (PMID 36151103, 2022). "A previous study showed that both S100B and GFAp in CSF increased similarly in a time and volume dependent manner after ischaemic stroke." (PMID 33723754, 2022).
ischemic stroke (continued). "Focal ischemic stroke of the right sensorimotor cortex was induced in adult GFAP-Cre × Rosa-YFP mice." (PMID 33841125, 2021). "The findings of increased NF-L and GFAP levels in the blood of ischemic stroke patients suggest that brain-derived proteins leak to the periphery quickly after the ischemic event." (PMID 33918875, 2021). "Acute ischaemic strokes of >100 cm3 reached >0.6% of glial fibrillary acidic protein+CD16+ monocytes within the first 2–8 h after hospitalization and subsided within 48 h." (PMID 33501422, 2021). "We were able to demonstrate a transient upregulation of NogoA on GFAP + reactive astrocytes for at least 2 weeks post-ischemic stroke in the marmoset." (PMID 34824275, 2021). "Astrocytes are the most abundant cells in the CNS and change to a reactive phenotype (so-called reactive astrogliosis) that is characterized by enhanced glial fibrillary acidic protein (GFAP) expression and cellular hypertrophy in response to ischaemic stroke." (PMID 33836646, 2021). "This process of reactive gliosis is characterized by a pronounced increase in GFAP and S100B, supporting their potential role as prognostic markers in ischemic stroke." (PMID 32595585, 2020). "The increase in AQP4 expression is in agreement with the increased cerebral water contents in Zone D; the decrease in GFAP expression corresponds to the finding that astrocytes in the infarct core are disrupted in ischemic stroke." (PMID 32985231, 2020). "Overall, GFAP cannot be considered a specific marker of hemorrhagic or ischemic stroke during the very early phase (0–2 h)." (PMID 31701356, 2020). "To further analyze the impact of EcoHIV on the kinetics of inflammatory processes following ischemic stroke, we next assessed protein levels of GFAP and Iba1." (PMID 31043599, 2019). "Clinical studies have demonstrated an increase in GFAP plasma levels after ischaemic stroke compared with control subjects, with a peak between day 2 and day 4 after onset of symptoms." (PMID 25029344, 2014). "Even a multi-center clinical trial was conducted to use GFAP to differential ICH from ischemic stroke." (PMID 24260364, 2013). "In fact, CDP-choline increased cell proliferation, vasculogenesis and synaptophysin levels and reduced glial fibrillary acidic protein (GFAP) levels in the peri-infarct area of the ischemic stroke." (PMID 24961534, 2013). "Although GFAP is not routinely employed as a clinical biomarker for ischemic stroke, its diagnostic and prognostic potential has been recognized in a range of neurological disorders." (PMID 41342963, 2025). "Furthermore, GFAP is less effective as a standalone biomarker for ischemic stroke detection and is best utilized in combination with other biomarkers or imaging modalities to enhance diagnostic accuracy." (PMID 40026944, 2025). "Importantly, larger infarcts are observed in GFAP−/−Vim−/− mice with ischemic stroke induced by middle cerebral artery transection, suggestive of the neuroprotective function of reactive astrocytes at the acute stage of ischemic stroke." (PMID 39080102, 2025). "Elevation of GFAP occurred at a much later time‐point of 48 h in ischaemic stroke patients." (PMID 39289040, 2025). "This hypothesis is supported by evidence comparing serum GFAP levels of intracerebral haemorrhage patients, who experience rapid blood–brain barrier disruption, to ischaemic stroke patients, where the opening of the blood–brain barrier occurs more gradually." (PMID 39289040, 2025). "Less is documented regarding the plasma or serum profile of GFAP after ischemic stroke." (PMID 40900222, 2025). "Higher GFAP expression during the chronic phase aligns with previous studies reporting a significant increase in GFAP expression within 12 h post-reperfusion in ischemic stroke models, persisting through subacute and chronic stages of ischemia, adding to long-term neuronal loss and reactive gliosis." (PMID 41342963, 2025).
ischemic stroke (continued). "In ischemic stroke C3d+/GFAP+ astrocytes aggravate blood–brain barrier (BBB) disruption." (PMID 39801259, 2025). "The microglia-selective marker Iba-1 (ionized calcium binding adapter molecule 1) and astrocyte marker GFAP (glial fibrillary acidic protein) were significantly elevated after PVD-induced ischemic stroke, and perampanel co-treatment prevented these elevated glial markers." (PMID 41148843, 2025). "Median plasma GFAP was 1214 pg/mL (IQR 147–8764) in patients with a primary cerebral cause of coma (including intracranial hemorrhage as defined above, ischemic stroke and CNS infection, but excluding epileptic seizures), and 35 pg/mL (IQR 29–64.5) in patients with other etiologies (p < 0.001)." (PMID 38581002, 2024). "In consequence, GFAP testing do not allow a reliable identification of ischemic stroke as the underlying coma etiology." (PMID 38581002, 2024). "The 5 patients who had their GFAP measurements completed in the prehospital phase showed the following GFAP values and diagnoses: 29 pg/mL (ischemic stroke), 58 pg/mL and 47 pg/mL (cardio-pulmonary event), 32 pg/mL (epileptic seizure), 10,001 pg/mL (intracerebral hemorrhage)." (PMID 38581002, 2024). "-GFAP successfully differentiated ischemic stroke from intracerebral hemorrhage within 6 h." (PMID 39459548, 2024). "A significant positive correlation (rs = 0.522; p = 0.002) between plasma GFAP levels and the degree of neurological deficit in patients with ischemic stroke, as measured by the National Institutional Health Stroke Scale (NIHSS) protocol, has been demonstrated previously." (PMID 38891898, 2024). "For instance, serum GFAP levels increased in patients with severe brain injury on admission and predicted neurological outcomes at six months, and they also correlated with the extent of brain damage and severity of the stroke in patients with ischemic stroke." (PMID 37958721, 2023). "During ischemic stroke, glial retraction occurs in the infarct core, whereas in the penumbra area, astrocytic activation and gliosis, featured with upregulate glial fibrillary acidic protein (GFAP), occurs in parallel." (PMID 35431804, 2022). "GFAP is considered the best candidate to date for differentiating hemorrhagic and ischemic stroke." (PMID 35813155, 2022). "In our study, we observed that ischemic stroke-induced neurodegeneration (loss of NeuN+ and GRP78+ neurons) in the peri-lesion cortex and striatum was associated with increase in reactive astrogliosis (elevated GFAP+/LCN2+ astrocyte counts)." (PMID 35440572, 2022). "In a study following ischemic stroke patients, serum GFAP values peaked 3–4 days after the initial insult, which indicates that the present study may have missed the GFAP peak." (PMID 35118644, 2022). "After 14 days of ischemic stroke, both immunolabeled GFAP+ reactive astrocytes and Iba-1+ microglia/macrophages exhibited phagocytic inclusions, including synapses and myelin-like structures within their cytoplasm, indicating that microglia/macrophages and astrocytes actively engulf synapses." (PMID 34836962, 2021). "Moreover, immunostaining of glial fibrillary acidic protein (GFAP) showed that reactive astrocytes in the ischemic stroke regions were significantly increased during cerebral IR injury but decreased following ABT263 treatment." (PMID 34769397, 2021). "In addition, serum GFAP levels were significantly increased in ischemic stroke patients [152.0 pg/mL (95.5; 297.5)] compared to healthy controls [90.5 pg/mL (52.5; 109.0), U = 74, p = 0.008)]." (PMID 33918875, 2021). "Following histopathological examination, immunofluorescent staining with antibodies against Pnn, a neuron nuclear antigen (NeuN), and glial fibrillary acidic protein (GFAP, a marker of astrocyte and ependymal cells) were performed on cryosections of cerebrum three days post ischemic stroke." (PMID 33027948, 2020).
ischemic stroke (continued). "Furthermore, plasma levels of GFAP were significantly higher in haemorrhagic stroke patients (mean value 111.6 ng/l) than in ischaemic stroke patients (mean value 0.4 ng/l)." (PMID 25029344, 2014). "After ischemic stroke, GFAP–/–Vim–/– mice develop larger infarctions than WT mice." (PMID 24223940, 2013). "GFAP levels were low in the vast majority of patients, with 98.5% of cases lying below the cut-off that was previously defined for the differentiation of intracerebral hemorrhage and ischemic stroke." (PMID 23626774, 2013). "Numerous studies have reported that transplanted MSCs in animals with ischemic stroke expressed the neural cell lineage markers, such as the neuronal-specific protein NeuN, microtubule-associated protein 2 (MAP-2), and the astrocytic marker GFAP." (PMID 21939558, 2011). "Besides, prior studies have shown that GFAP released within 3–4 h following hemorrhagic stroke, while it released within 24–48 h post injury in ischemic stroke, strongly showing that GFAP might be a key marker that can discriminate these two." (PMID 38216970, 2024). "In addition, some studies have proved that serum markers had a certain advantage in distinguishing hemorrhagic stroke and ischemic stroke, including glial fibrillary acidic protein (GFAP), N-terminal proB-type natriuretic peptide (NT-proBNP), and retinol-binding protein 4 (RBP-4)." (PMID 36864378, 2023). "In addition, serum GFAP levels were increased in patients with severe brain injury on admission and significantly predicted neurological outcomes at six months, and elevated levels of serum GFAP were significantly correlated with the extent of brain damage in ischemic stroke patients." (PMID 37958721, 2023). "Together, these results indicated that administration of 70 mg/kg ambroxol could increase the percentage of DCX+ cells, while decrease the portion of GFAP+ cells in penumbra, to some degree, induced by ischemic stroke, and finally reduced infarct volume to potentiate functional recovery." (PMID 33551744, 2020). "Note that, in ET-1 injected areas, NeuN significantly reduced across all injury areas, whereas GFAP signal also reduced in the lesion core areas but significantly increased in the peri-infarct areas, suggesting that astrocytes became reactive at 3 weeks following ischemic stroke." (PMID 33224952, 2020). "We determined the effect of modulation of glial scar stiffness on neurological recovery after ischemic stroke by quantifying the numbers of EdU+DCX+ and EdU+CD31+ cells in the peri-infarct area of GFAP-ChR2 and GFAP-Arch mice." (PMID 41346705, 2026). "In ischemic stroke, SERPINA3 has been proposed as a potential replacement of glial fibrillary acidic protein (GFAP), a traditional biomarker for activated astrocytes." (PMID 40157917, 2025). "Glial fibrillary acidic protein (GFAP), a protein present in the soma and end-feet of astrocytes, has been identified as a promising candidate for differentiating haemorrhagic from ischaemic stroke." (PMID 40117100, 2025). "Other neuroaxonal injury markers—including tau, UCH-L1, and glial fibrillary acidic protein (GFAP)—may capture complementary aspects of neuronal or glial pathology; however, their temporal dynamics and peripheral detectability are less consistent than NfL in ischemic stroke." (PMID 41303115, 2025). "In this study, we charted the temporal profile of GFAP, NFL, t-tau, and UCHL1 concentrations in plasma following an ischemic stroke by analyzing daily blood samples collected throughout the first week after symptom onset." (PMID 40900222, 2025). "For example, GFAP levels increase within 2–6 h in hemorrhagic stroke, whereas NFL rises acutely in ischemic stroke." (PMID 41227149, 2025). "Our results are consistent with the existing literature, highlighting elevated GFAP and UCH-L1 levels in hemorrhagic stroke versus ischemic stroke, and differentiating between large and small vessel occlusions." (PMID 40649119, 2025).
ischemic stroke (continued). "Quantitative immunohistochemical analysis revealed the beneficial effect of BHD treatment on the neurogenesis in the peri-infarct area following ischemic stroke, as evidenced by the elevated cells number of Ki67+, Ki67/MAP-2+ and Ki67/GFAP+." (PMID 40973940, 2025). "Brain natriuretic peptide (BNP) and glial fibrillary acidic protein (GFAP) have risen as prominent candidates in this field, offering the potential to revolutionize both the early diagnosis and prognostication of ischemic stroke." (PMID 40026944, 2025). "It was observed that ischemic stroke patients exhibited elevated levels of RBP-4, NT-proBNP, and endostatin, while they had lower levels of GFAP than ICH patients." (PMID 37892701, 2023). "C3d+/GFAP+ astrocytes aggravate BBB disruption, suggesting that inhibiting C3d+/GFAP+ astrocyte formation represents a novel strategy for the treatment of ischemic stroke." (PMID 35656116, 2022). "This early increase in GFAP is an expression of an increased blood brain barrier disruption, and astroglial destruction in ICH patients, compared to ischemic stroke patients." (PMID 33546160, 2021). "Furthermore, FISH and IF revealed that these increased miRNAs regulated by EA mainly occur in neuronal cells of cortex and less in GFAP-positive cells, demonstrating that EA might exert a potential protective effect of ischemic stroke through regulating these miRNAs in brain neuronal cells." (PMID 34566862, 2021). "Taken together, these data provide substantive evidence that NogoA expression on GFAP + reactive astrocytes contributes to the corralling of LILRB2 + infiltrating monocytes and macrophages in the primate brain post-ischemic stroke." (PMID 34824275, 2021). "On the other hand, plasma GFAP has been used to differentiate between intracranial hemorrhage (ICH) and ischemic stroke, with high sensitivity and specificity." (PMID 30034558, 2018). "F1, F5, and F9 treatments notably reduced the levels of GFAP and VEGF activity in the ischemic stroke." (PMID 28400733, 2017). "This review article aims to provide an overview of GFAP in the prediction of clinical progression in neuroinflammation, brain tumors, TBI, ischemic stroke, genetic disorders, neurodegeneration and other diseases in the CNS and to explore the potential therapeutic methods." (PMID 38216970, 2024). "Numerous studies focused on the role of GFAP in differentiating intracerebral haemorrhage (ICH) and ischaemic stroke suggesting that GFAP may be a potential biomarker for an early prediction of ICH." (PMID 39595521, 2024). "For instance, it is well-established that blood GFAP elevations are not exclusive to AD, as they are also observed in other acute CNS conditions such as ischemic stroke or traumatic brain injury." (PMID 39080712, 2024). "Our results showed that PDGF-D did not affect the reactivity of GFAP+ cells nor that of IBA1+ cells at the lesion site 2 weeks after ischemic stroke." (PMID 38769116, 2024). "PDGF-D increased subacute bioavailability did not alter the projections of reactive GFAP+ astrocytes, indicating a preservation of the anisomorphic phenotype 2 weeks after ischemic stroke (VEH:36.41 ± 1.078; P125:37.833 ± 1.115; P250:37.638 ± 1.661)." (PMID 38769116, 2024). "Another study demonstrated that GFAP concentrations were associated with both hematoma volume and neurological severity in ICH patients, while no such correlation was observed in ischemic stroke patients." (PMID 37892701, 2023). "Our current studies further clarified that the reduced GFAP, neurocan, and phosphacan expressions are not simply due to the reduced brain injury in the acute stage of ischemic stroke with RIPK inhibition." (PMID 33629276, 2021). "Combination of GFAP and NR2 antibodies discriminated ischemic stroke vs. ICH." (PMID 33115334, 2021). "GFAP was correlated with ICH volume that allowed to differentiate between ICH and ischemic stroke." (PMID 33115334, 2021).